MC4R (melanocortin 4 receptor)
Diseases named in the same sentence as MC4R in open-access papers (continued):
Sharing a sentence is not in itself a finding about the gene and the disease.
Obesity (continued). "During the early stages of the development of obesity, MC4R+/− animals that are not receiving an already rewarding high-fat diet display an increase in motivation towards food-related rewards." (PMID 39741559, 2024). "Our results that chronic activation in both POMC and MC4R neurons does not affect body weight reduction or obesity prevention are somewhat surprising." (PMID 37069175, 2023). "Despite potential sympathetic adverse effects, one MC4R agonist emerging therapy undergoing clinical trials for treating generalized non-diseased obesity called RM-493 (Clinicaltrials.gov ID: NCT02041195; Clinicaltrials.gov ID: NCT01749137)." (PMID 37937009, 2023). "Furthermore, gain of function of the melanocortin action through overexpression of MC4R, POMC or its derived peptides had little effect on obesity prevention or reversal." (PMID 37069175, 2023). "Contrarily, MC4R deficiency in humans and rodents induce insulin resistance and obesity but do not develop hyperglycaemia, which is in line with the finding that MC4R agonists improve insulin secretion in diabetic mice." (PMID 37638032, 2023). "HFD-fed Mc4r-KO mice, but not HFD-fed ob/ob mice, progress from NAFL to NASH and hepatocellular carcinoma in association with the development of obesity and insulin resistance." (PMID 37681411, 2023). "Another essential gene for obesity, MC4R was not selected because it was filtered out for having less than three SNPs mapped." (PMID 37205363, 2023). "Similarly for the MC4R gene, the presence of the C allele leads to increased eating pleasure, reduced satiety, and a tendency to eat when not hungry, which may contribute to obesity." (PMID 38066615, 2023). "Body weight reduction was observed in several animals with obesity of genetic origin treated with setmelanotide; however, the same results were not seen in MC4R knockout mice." (PMID 37888071, 2023). "However, in our case patients, the location of this POMC variant, together with the high ACTH levels, strongly suggests that their obesity and hyperphagia were indeed the consequence of impaired PC2 cleavage and thereby impaired activation of MC4R." (PMID 35737586, 2022). "Microdosing also failed to correct obesity in DIO mice and in obese melanocortin 4 receptor (MC4R)-deficient mice." (PMID 35953488, 2022). "The PVN demonstrates the highest level of MC4R expression within the CNS, and the disruption of MC4R in the PVN results in hyperphagia and reduced energy expenditure, leading to the development of the obesity phenotype." (PMID 35328759, 2022). "Significant differences were found in weight of all participants (p ˂0.001) and obese subjects (p = 0.008), waist circumference of individuals with obesity (p = 0.03) and all subjects (p = 0.001) and WHR of all participants (p = 0.02) between different genotypes of MC4R." (PMID 36123585, 2022). "This study demonstrates that the CC genotype of MC4R rs17782313 is more common in patients with T2D, but not prediabetes or obesity." (PMID 35292917, 2022). "It has been shown that defects in MC4R can lead to a clinical phenotype defined by lack of satiety and early-onset obesity." (PMID 35571924, 2022). "Genetically modified null MC4R mice models exhibit obesity, insulin resistance, nonalcoholic steatohepatitis (NASH), nonalcoholic fatty liver disease (NAFLD), fibrosis, and hepatocellular carcinoma (HCC)." (PMID 35268815, 2022). "Regarding autosomal dominant genes, a significant difference in the number of carriers with and without obesity was found for the MC4R gene [p=0.026 (0.007-0.0622]." (PMID 35574020, 2022). "The MC4R, a GPCR, has long been a major target for obesity treatment." (PMID 35818295, 2022). "For example, melanocortin receptor 4 (MC4R) agonist melanotan II produces its anorectic effects through coupling to Gq/11 and its adverse cardiovascular effects through Gs coupling, suggesting potential therapeutic benefit in obesity for Gq/11-biased ligands." (PMID 34576254, 2021).
Obesity (continued). "In this case, obesity is a consequence of the lack of POMC‐derived peptide signalling in MC4R‐expressing neurons, resulting in a chronic orexigenic state." (PMID 34156126, 2021). "WD-fed MC4R KO mice are known to exhibit pathophysiological changes of NASH including hepatic steatosis, liver fibrosis and hepatocellular carcinoma following the obesity-related phenotype." (PMID 31990961, 2020). "Taken together, the findings of the study suggest that overexpressed DNAJC27 reduces cAMP formation by wild-type MC4R, and this provides a potential mechanism of action for the effect of elevated circulating DNAJC27 on appetite and eventually the development of obesity." (PMID 32733386, 2020). "As in mammals and birds, MC4R, AgRP, POMC, and MRAP2 have also been identified in some teleost species, and these molecules likely play similar roles in feeding, growth, and obesity within the hypothalamus." (PMID 32987823, 2020). "Besides the FTO, Melanocortin 4 Receptor (MC4R) and Transcription Factor 7-Like 2 (TCF7L2) genes are the two commonly studied candidate genes for obesity and T2D." (PMID 32397403, 2020). "Although studies suggest that MC4R signaling interacts with BDNF-TrkB signaling in the context of body weight regulation, it is unlikely that Ntrk2 deletion in the PVH leads to obesity through the MC4R because the deletion did not reduce levels of Mc4r mRNA." (PMID 32265438, 2020). "For example, four gene loci of SEC16B rs543874, MC4R rs17782313, MAP2K5 rs2241423, and KCTD15 rs11084753 were found to be significantly correlated with obesity in Chinese children and adolescents after adjusting for age and sex, and had an interaction with dietary behavior." (PMID 32111069, 2020). "Among these, only survival probability of KIRC patients could be impacted by gender and expression levels of four obesity-elated genes (LEP, MC4R, TMEM18, and PCSK1)." (PMID 33299884, 2020). "Many genes implicated in monogenic obesity have also been flagged in these large-scale obesity GWAS, including LEPR, MC4R, and POMC, although they are usually not the most prominent findings." (PMID 33233816, 2020). "Combining WD with MC4R KO mice, which induces substantial obesity and insulin resistance compared to the high fat diet-fed normal mice, is an attractive NASH model with significant fibrosis." (PMID 31990961, 2020). "Mice lacking Mc4r expression have increased food intake and decreased energy expenditure, resulting in obesity and hyperinsulinemia." (PMID 31681175, 2019). "It is suggested that the MC4R signalling pathway is affected secondary to the impairment of interaction with MC4R and α-MSH in heterozygous missense POMC variants without complete POMC deficiency, and subsequently severe obesity develops in humans." (PMID 30991789, 2019). "We performed SDV as a “preventative” measure in 3- to 5-month-old Mc4r−/− mice that had not yet attained full obesity (< 45 g) and as a “reversal” measure in 8-month-old Mc4r−/− mice that were severely obese (>50 g)." (PMID 29545738, 2018). "Interestingly, these data suggest that MC4R and KSR2 were identified as having a role in common, complex obesity." (PMID 30121879, 2018). "These novel findings provide important evidence that adiponectin may be possibly mediate the process of MC4R and BDNF involved in obesity." (PMID 28396685, 2017). "Another encouraging therapeutic approach is the use of a selective MC4R agonist, which has been proven successful in the treatment of POMC-deficient obesity as well as in humans with non-genetic obesity and in non-human primates." (PMID 28592656, 2017). "Moreover, recent reports of obesity-related loci enriched in brain-expressed genes such as FTO, MC4R, GNPDA2, and BDNF point to a neuronal influence on body weight regulation in adults." (PMID 29212175, 2017). "As the focus of this review is on common polygenic obesity, the examples of INDELs in MC4R which lead to rare monogenic obesity will not be further discussed here." (PMID 28615046, 2017).
Obesity (continued). "This implicates a larger role of hyperphagia in the obese phenotype seen in rats lacking functional MC4R4, 12, and potentially in human obesity seen with altered MC4R." (PMID 27886210, 2016). "Data from our extensive phenotypic comparison suggested that Mc4r KO and DKO might be good rat models for obesity or type 2 diabetes (T2D)." (PMID 27713523, 2016). "Unlike obesity in Sim1 or Mc4r mutant mice, the obesity induced in the high-fat diet rodent model is relevant to human obesity which is strongly associated with the recent availability of high-calorie food." (PMID 27585985, 2016). "The Mc4r KO and DKO rats generated in our lab will be beneficial for future studies to further elucidate MC3R and MC4R’s function and signalling pathways, and provide better rat models for novel anti-obesity or anti-diabetic drug development." (PMID 27713523, 2016). "Mc4r-null mice feature hyperphagic obesity without pathologically suppressed leptin levels, suggesting that they have the potential to model the extended spectrum of NAFLD more faithfully than ob/ob mice." (PMID 27899914, 2016). "Both Mc4r KO and DKO are good models for obesity and diabetes research." (PMID 27713523, 2016). "Expression of MC1R, MC4R and MC5R has been suggested in the adipose tissue of human obese subjects and these receptors may reflect an aspect of the pathophysiology of human obesity." (PMID 26459134, 2015). "Mice lacking MC4R had the elevated insulin level and the decreased insulin sensitivity even before manifestation of hyperphagia and obesity." (PMID 28031898, 2015). "We show that combination therapy of the MC4R agonist RM-493, which has shown to be highly selective and safe in terms of its cardiovascular profile, with the GLP-1R agonist liraglutide potently reverses diet-induced obesity and improves glucose metabolism." (PMID 25652173, 2015). "While the melanocortin 4 receptor (MC4R) has often been the target for obesity treatment, to the best of our knowledge no dimerization between GHSR1a and MC4R has been identified." (PMID 26464979, 2015). "The pre-surgery BMIs of patients with rare variants were not different from patients with the MC4R reference allele, due to the RYGB selection criteria and the multiple genetic and environmental factors that can contribute to obesity." (PMID 24705671, 2014). "Although the mechanism of most genetic loci predispose individuals to obesity is not clear so far, evidence indicated that they were involved in energy uptake (FTO, MC4R, PCSK1, and BDNF) and adipocyte differentiation (FTO, TMEM18, BDNF, MTCH2 and NEGR1)." (PMID 24626232, 2014). "Besides using a genetic risk score, we separately analyzed effects of two well-established obesity loci, FTO and MC4R, on BMI." (PMID 24040077, 2013). "Reactivation of MC4R specifically in cholinergic preganglionic sympathetic and parasympathetic neurons located in the dorsal motor nucleus of the vagus (DMV) attenuates obesity and hepatic, but not skeletal muscle, insulin resistance seen in MC4R null mice." (PMID 23550218, 2013). "SNPs in SH2B1, SFRS10 and KCTD15 associated with increased risk of overweight, but not with obesity, while the risk alleles in MC4R and NEGR1 associated with increased risk of obesity, but not with overweight." (PMID 23861046, 2013). "None of the genotyped variants in genes for monogenic obesity reached genome-wide significance in our GWAS, although several variants in CRHR1, CRHR2, MCHR1, MC3R, MC4R and POMC were nominally associated." (PMID 23251661, 2012). "However, on considering the aggregate score of the MC4R rs17782313 and FTO rs9939609, we did observe a statistically significant interaction both for BMI and for obesity." (PMID 23284998, 2012). "However, similar to the FTO gene, not all individuals possessing MC4R gene variants are overweight or obese, again suggesting that possible interactions with other genetic and/or environmental factors could be necessary for promoting weight gain and obesity." (PMID 22043166, 2011).
Obesity (continued). "PH MC4R mRNA expression was significantly reduced by HFD consumption, as well as litter size reduction (P<0.05, HFD and litter effects); whereas it was increased by maternal obesity (P<0.05, maternal effect)." (PMID 19606226, 2009). "The melanocortin-4 receptor (MC4R) is primarily expressed in the mammalian brain, plays an important role in body weight regulation, and is a lead target for the treatment of obesity." (PMID 17668051, 2007). "Although specific MC4R mutations are not typically associated with SMS, altered functioning of this pathway may contribute to the increased obesity risk observed in affected individuals." (PMID 40443456, 2025). "As an obesity control, we also tested autophagy flux in Mc4r+/− mice, as they display a comparable adiposity with Mc3rTB/TB mice, though not as severe an obesity phenotype as is seen in Mc4r−/− mice." (PMID 39956805, 2025). "However, a more detailed study of Mc4r-deficient mice incorporating younger ages, suggests that excessive fat deposition may occur already at weaning without initially affecting body weight, suggesting obesity may develop or present differently during the life course in mice compared to humans." (PMID 40702736, 2025). "Besides the MC4R‐targeted treatment, glucagon‐like peptide‐1 (GLP‐1) receptor agonists (such as semaglutide) in combination with lifestyle interventions can reduce body weight in individuals with overweight or obesity." (PMID 40186386, 2025). "Overall, the results suggest that individuals with MC4R gene variations exhibit BED, characterized as severe and associated with MetS, compared to matched individuals with severe obesity who are non-carriers of gene abnormalities and do not engage in binge eating." (PMID 40077044, 2025). "Mouse models depleted of MRAP2 have extreme obesity, increased fat mass and visceral adiposity, analogous to MC4R knockout mice; while double knockouts of MRAP2 and MC4R further demonstrated that MRAP2 facilitates the action of MC4R, but that there are also MC4R-independent mechanisms." (PMID 39807633, 2025). "After obesity was well established, the MC4R+/− animals fed the control diet no longer showed increased motivation to work for sucrose rewards, and in the presence of distracting stimuli, displayed a prominent decrease in motivation to work for sucrose rewards." (PMID 39741559, 2024). "MC4R, predominately expressed in the paraventricular nucleus that receives projections from the ARC, is known to regulate food intake, body weight, and energy homeostasis, and consistently, lack of function of this receptor in mice and humans results in hyperphagia and obesity." (PMID 39129011, 2024). "MC4RF51L mice develop obesity without disruption of MC4R/Gsα/cAMP signaling." (PMID 38175730, 2024). "However, the role of Kir7.1 in body weight regulation is unclear, as Kir7.1-null mice only develop mild obesity at a very late age, which does not mimic the phenotype of MC4R-null or MC4RF51L mice." (PMID 38175730, 2024). "MC4R defects, which can disrupt the melanocortin pathway, lead to a clinical phenotype characterized by an increase in appetite, lack of satiety, and early-onset obesity." (PMID 39458497, 2024). "We next built a prioritization score that weighs each of the eight methods based on whether or not they prioritized one or more of the six established obesity genes located in any of the 536 BMI-associated loci (i.e., LEPR, POMC, PCSK1, DGKI, SH2B1, and MC4R)." (PMID 38754426, 2024). "Thus, MC4R neurons in the forms of increased neuron activity or overexpression of MC4Rs both failed to reduce body weight on chow or prevent obesity on HFD." (PMID 37069175, 2023). "Since MC4RKO mice exhibit obesity, we originally hypothesized that the metabolic effects of the absent MC4R might alter sexual behavior." (PMID 37033219, 2023).
Obesity (continued). "However, the mechanisms of such suppression appear to differ between the 2 mouse models of genetic obesity, with hepatic FASN deficiency attenuating PPARα activity and activating AMPK in ob/ob mice but not in Mc4r-KO mice." (PMID 37681411, 2023). "According to our knowledge, there are no comparable studies that compare HBI and markers such as MC4R (rs17782313), CAV-1 (rs3807992), and Cry-1 (rs2287161) with abdominal obesity and obesity-related metabolic risk factors in overweight and obese women across time." (PMID 36167582, 2022). "The main strength of the present study is that although several studies have assessed the interaction of MC4R and diet on metabolic syndrome, diabetes, and obesity, no investigations have been conducted to assess the interaction between MND and MC4R rs17782313 polymorphism on CVD risk factors." (PMID 36050672, 2022). "Therefore, we examined the inhibitory effect of daisaikoto on obesity and NAFLD using MC4R-KO mice." (PMID 35710868, 2022). "Notably, in a heterozygous MC4R murine knockout model, although energy balance was disrupted, causing obesity, these mice responded well to RYGB surgery, suggesting that the presence of a single functional MC4R copy does not impair RYGB-induced weight loss." (PMID 36553534, 2022). "Even though some of them already showed acceptable MC4R selectivity and preclinical efficacy, their clinical trial results for obesity treatment were not satisfying because of severe side effects including increased blood pressure, increased heart rate, vomiting, nausea and sex arousal." (PMID 35818295, 2022). "The loss of such anorexigenic signals through MC4R could produce hyperphagia, but this hypothesis has not been widely studied in AHO individuals with obesity." (PMID 36232301, 2022). "Among the available phenotypes, obesity was chosen because it has been subjected to a number of high quality and well-powered GWAS that have identified more than 100 loci, many that have been consistently replicated across studies (e.g. FTO, BDNF, MC4R, TMEM18, SEC16B)." (PMID 33947323, 2021). "An agonist of the MC4R, used in individuals with severe obesity due to either POMC, PCSK1, or LEPR deficiency, and should not be used for other types of obesity such as general obesity." (PMID 34552557, 2021). "MC4R is a downstream target of leptin signaling and mice lacking MC4R developed obesity." (PMID 33716966, 2021). "Leptin has been shown to be increased in obese patients and to mediate the development of obesity hypertension in studies using non-pregnant rodents; this occurs via downstream signaling of the melanocortin-4 receptor (MC4R) in the brain that promotes sympathetic drive and hypertension." (PMID 32817646, 2020). "Interestingly, these genes, with the exception of MC4R, KSR2 and GIPR, have not previously been implicated in obesity, suggesting that key biologic mechanisms underlying obesity have yet to be identified." (PMID 32955435, 2020). "Combining these data suggests that apparently poorly brain penetrant MC4R agonists (below analytical detection levels) with a unique receptor activation pharmacology profile may show promise for the treatment of obesity without the CV side effects." (PMID 31100979, 2019). "In this study, we compared gene expression profiles of activated fibroblasts prepared from two distinct liver fibrosis models: MC4R-KO mice on WD and chemically induced liver fibrosis using carbon tetrachloride (CCl4) as a model of fibrosis without obesity and HCC development." (PMID 31862949, 2019). "Additionally, Mc4r−/− mice that have not yet attained full obesity, exhibit reduced locomotor activity that is accompanied by a higher respiratory exchange ratio." (PMID 29545738, 2018).